WT1 (WT1 transcription factor)
Diseases named in the same sentence as WT1 in open-access papers (continued):
Sharing a sentence is not in itself a finding about the gene and the disease.
tumor (continued). "Others have demonstrated that the tumor suppressors p63, p73 and WT1 positively regulate Wnt4 expression while p21 has the opposite effect, suggesting that maintenance of appropriate Wnt4 expression may also be critical for adult tissue homeostasis and prevention against tumor initiation." (PMID 20161747, 2010). "We next analyzed the effect of cytotoxic drugs on HtrA2-mediated cleavage of WT1 in the tumor-derived cell lines U2OS and H1299, which both express endogenous WT1." (PMID 20122399, 2010). "11p13 (WT1 locus) and 11p15.5 (WT2 locus) are known to have genetic or epigenetic aberrations in these tumours." (PMID 16909133, 2006). "Since this tumour also had concurrent 11p13 LOH, ‘two-hit’ inactivation (LOH and methylation) led to a reduction of WT1 expression." (PMID 16909133, 2006). "Tumor cells in effusions from patients 1 and 2 and, the smear obtained by FNA (Patient 1) were positive to WT1." (PMID 15777480, 2005). "Tumor cells in effusions and FNA were positive to WT1 in 3 of 4 cytology specimens (2 out 3 effusions and one FNA)." (PMID 15777480, 2005). "The IHC staining was positive for CD99 and FLI-1 (in >50% of tumor cells) and negative for AE1/AE3, INI-1 loss, WT1, desmin, myogenin, BCOR, TLE-1, CD45CLA, and synaptophysin." (PMID 41230381, 2026). "The NF-κB complex activates the transcription of inflammatory cytokine genes, in addition to mobilizing the Wilms tumor protein - WT1 (already reported to be overexpressed in KS lesions and other tumors), which creates a favorable microenvironment for tumor development." (PMID 41563473, 2026). "In WT1-driven tumors, the extent of LOH corresponded to the ipsilateral primary tumor." (PMID 40340749, 2025). "Notably, overexpression of the miRNA signature downregulated the Androgen Receptor (AR) expression via WT1 and FOXA1 repression, impaired the tumor-sphere forming ability of cells and was able to reverse cancer stemness." (PMID 40399259, 2025). "Histology showed the excised lesion to be a JGCT; tumor cells were immunostained for CKAE1/AE3 (focally in a “dot-like” juxtanuclear pattern), vimentin, inhibin, CD56, CD99, WT-1, PR, and focally for calretinin (again, any IHC was indicative of the presence or absence of these proteins)." (PMID 40076617, 2025). "Another dendritic cell vaccine with WT1 protein mRNA (NCT01291420) showed striking tumor reduction (ORR) in 50% of 40 hormone receptor-negative/HER2-negative metastatic breast cancer (HR−/HER2 − MBC) patients at 6 months posttreatment." (PMID 41179878, 2025). "Tumor cells were immunostained for CKAE1/AE3, inhibin, calretinin, WT-1, and focally for melan-A." (PMID 40076617, 2025). "Immunohistochemistry showed that tumor cells were AE1/3 (+), S-100 (–), Desmin (–), WT1 (–)." (PMID 40034204, 2025). "Since WT1 represses the SGK1 promoter, SGK1 might act as a tumor suppressor in this context by inducing the differentiation of leukemic cells." (PMID 40613901, 2025). "Transduction of M02 primary tumor cells with a GFP-luc vector led to selection of cells that no longer expressed WT1." (PMID 41413213, 2025). "This is consistent with earlier reports on sporadic tumors with nephrogenic rests, where WNT activation in WT1-driven cases was limited to tumor tissue but absent from nephrogenic rests." (PMID 40340749, 2025). "The tumor cells were diffusely positive for α-inhibin, SF1, FOXL2, WT1, and Vimentin." (PMID 41584573, 2025). "In our case, the tumor showed strong and diffuse immunoreactivity for WT1 and CD10, with absent cyclin D1 expression." (PMID 41464215, 2025). "Tumor cells were positive for α-inhibin, SF-1, FOXL2, WT-1, and Vimentin." (PMID 41584573, 2025). "WT1 and SGK1 can act as oncogenes or tumor suppressors, depending on the context." (PMID 40613901, 2025).
tumor (continued). "On immunostaining, the tumour cells expressed inhibin, calretinin, vimentin, ER, WT1 and CK7 and were negative for EMA." (PMID 38376618, 2024). "The low T cell infiltration observed in areas of high WT1 and LANA suggests that WT1 may contribute to the immunosuppressive functions of KSHV in creating an immunosuppressive tumor microenvironment." (PMID 38190392, 2024). "Specifically, we aimed to further elaborate upon previous promising seminal IHC findings, focusing on the biological significance and comparative relationship between novel immunoexpression patterns for WT1 antigen and TDs, in adult RCC tissues and their corresponding tumor-adjacent HRTs." (PMID 38929778, 2024). "One potential alternative explanation is that androgen is necessary for the formation of the EWSR1::WT1 fusion but not subsequent tumor growth." (PMID 38575753, 2024). "Importantly, the WT134‐51 helper peptide, which can be utilized for all MHC class II types, significantly contributes to tumor eradication not only through CD4+ Th1 cells, but also WT1-specific CD8+ CTLs in antitumor immunity." (PMID 39737308, 2024). "With the exception of one tumor, the morphology of the epithelial component of the studied CS was of HGSC, the former tumor having endometrioid features and staining negative for WT1." (PMID 38733380, 2024). "On immunostaining, the tumour cells showed strong expression of calretinin, inhibin, vimentin, WT-1 and oestrogen receptor (ER) and were negative for cytokeratin 7 (CK7), and epithelial membrane antigen (EMA)." (PMID 38376618, 2024). "We detected no consistent difference in cell proliferation, expression of epithelial or fibroblast lineage markers, nor indeed in the expression of WT1, in size-matched tumours from Cre-induced CNP mice with or without exposure to asbestos." (PMID 37441092, 2023). "Tumor volume, the frequency and phenotypes of WT1-specific CTLs in CD8+ T cells in peripheral blood (PB) and tumor-infiltrating lymphocytes (TILs), as well as the proportion of interferon-gamma (INF-γ)-producing CD3+CD4+ T cells pulsed with WT135–52 peptide in splenocytes and TILs were determined." (PMID 36803483, 2023). "The isolated splenocytes were then stimulated by WT1 peptides in the presence/absence of tumor cells and incubated with either anti-PD-1 or an isotype control antibody." (PMID 36138335, 2023). "In the cultures without tumor cells, WT1-specific CD8+ T cells from mice treated with nelatimotide-only Emulsion produced similar amounts of IFN-γ in the presence of anti-PD-1 or isotype control antibody." (PMID 36138335, 2023). "In parallel, the scRNA data from 15 PDAC tissues samples also showed higher infiltration of cells expressing SMC/fibroblast markers (PDPN, COL5A1, COL22A1, TIMP3, SPARC, WT1, GFPT2) in samples with higher proportions/fractions of MUC16-expressing tumor (epithelial) cells (n = 7)." (PMID 36816942, 2023). "Tumor cells diffusely and intensely express WT1, FOXL2, and SF1, but are usually negative for EMA, AE1/AE3, inhibin, and calretinin." (PMID 38136408, 2023). "No cytotoxicity was observed against WT1-HLA-A*02:01- tumor cell line K562, confirming that introduction of a second anti-WT1-HLA-A*02:01 Fab on the distal arm did not result in elevated nonspecific binding." (PMID 38022650, 2023). "While in this case of ALES, the tumor cells did not express desmin and WT1 and was negative for diagnostic-specific EWSR1-WT1 translocation." (PMID 37518334, 2023).
tumor (continued). "Immunohistochemically, the tumor cells were positive for CK, calretinin, D2-40, WT-1, and vimentin, and negative for Paird box 8, synaptophysin, chromogranin-A, inhibin-α, S-100, Melan-A, HMB45, and CD34." (PMID 38115250, 2023). "Actually, in the oncological setting, for a variety of adult epithelial neoplasms, WT1 immunoreactivity has more often been documented in vascular and stromal tumor components, as opposed to the actual epithelial-derived tumor cells." (PMID 35453662, 2022). "Immunohistochemical staining showed that the tumor cells were positive for vimentin and Bcl-2 but negative for S-100, desmin Syn, WT-1, EMA, CD34, and CD99; the Ki-67 index in tumor cells was 40%." (PMID 36482604, 2022). "Most recently, WT1-specific CTLs were regenerated from allogeneic homozygous human leukocyte antigen (HLA) haplotype–induced pluripotent stem cells (iPSCs) and have shown therapeutic efficacy in a patient-derived RCC xenograft tumor model." (PMID 35453662, 2022). "The treatment of these mice with genetically modified WT1-specific TCR-T cells significantly reduced tumor growth and enhanced survival without inducing GVHD." (PMID 35356211, 2022). "Depletion of CD8+ T cells dramatically prevented CRC development in mice colonized with WT2 microbiota but had no inhibitory effects on tumor growth in mice gavaged with WT1 microbiota." (PMID 36726985, 2022). "Tumor development impairment was evident macroscopically in the WT1-positive tumors, while no response was seen in the WT1-negative tumors." (PMID 35453662, 2022). "Immunohistochemically, the tumor cells were positive for CD117, vimentin, CD56 and NSE and focally expressed desmin; the cells were negative for myogenin, S-100, SYN, INSM1, CD34, STAT6, INI-1, Brachyury, ERG, TLE1, AE1/AE3, WT-1, CD99 and SMA." (PMID 35488288, 2022). "The CNVkit SCNA analysis also highlights the potential importance of oncogenes (e. g., RCP, CD44, WT1, BCL2L2, and AKT2) and tumor suppressors (e. g., PRKCDBP) to TNBC etiology and metastatic progression, as significant amplicons/deleted regions harbor these genes." (PMID 35992833, 2022). "For example, WT1 expression in CRC primary tumors could be a novel independent marker for prognosis and tumor progression." (PMID 34266354, 2021). "Molecular characterization of the CAM tumor employing markers such as cyclin D2, ETV4 or WT1 could thus be carried out." (PMID 34685592, 2021). "The efficacy of the combined HAGE/WT1 ImmunoBody® vaccines was then tested in both prophylactic and therapeutic settings in female HHDII/DR1 mice (n=10/group) using the aggressive hB16/HAGE+/Luc+ tumour." (PMID 34262856, 2021). "The expression of the EWSR1-WT1, a fusion protein containing sections of EWSR1 and WT1 transcription factor, in proliferative small round cell tumors can induce the expression of IL-2 and IL-15, which are related to the proliferation of these tumor cells." (PMID 34124041, 2021). "This behavior is related to the tumor status of the analyzed cell lines, as it was observed that only the ER-positive cell lines expressed the 52-54 kDa WT1 isoform; this was absent in the ER-negative cell lines." (PMID 34845427, 2021). "Interestingly, eight among the overlapped hypermethylated genes (WT1, PAX6, GNAS, EPB41L1, CSMD1, CPEB1, RERG, and SMAD6) were previously reported to exhibit tumor suppressive functions." (PMID 34462486, 2021). "Immunostaining of tumor cells is usually diffusely positive for epithelial markers (AE1/AE3, CAM5.2, CK7) and is also positive for mesothelial markers, such as D2-40, calretinin, WT-1, and HBME-1." (PMID 34248850, 2021).
tumor (continued). "Based on the results of preclinical studies, future randomized clinical trials should be designed to evaluate vitamin C activity in specific tumor molecular subtypes, such as those characterized by HIF-1α over-expression and TET2, L2HGDH, IDH1/2, or WT1 altered pathways." (PMID 33804775, 2021). "Immunohistochemical staining revealed the cells of the tumor to be negative for the WT1 tumor suppressor gene." (PMID 35187045, 2021). "Following vaccination, WT2725 (a synthetic WT1 peptide) has potential to stimulate the host immune system to induce a CTL response against cancer cells that overexpress the WT1 protein, leading to cell lysis and preventing further tumor cell proliferation." (PMID 34785698, 2021). "WT1 is a transcription factor that regulates many cellular pathways, including WNT and MAPK signaling, and is involved in processes like cell differentiation and tumor suppression." (PMID 33804775, 2021). "Since it is evident that the combination vaccine can induce a more robust anti-tumor immunity than can CTL peptide vaccine alone, the FDG uptakes in WT1-vaccinated skin might reflect the degree of immune response." (PMID 32991475, 2020). "WT1 is overexpressed in the majority (>80-90%) of patients with AML, including cell-cycle quiescent AML stem cells located in the BM and relapses after CBT, which supports the choice of WT1 as a tumor target." (PMID 33101274, 2020). "In two of the three patients with somatic WT1 mutations, Wilms3 and Wilms11, no mutations in CTNNB1 were observed in the cell lines in comparison to the tumor DNA carrying a p.T41A and a p.S45F CTNNB1 mutation, respectively." (PMID 33379206, 2020). "To examine whether the WT1-CTLs are effective against solid tumors, we selected RCC as a target tumor and used three RCC cell lines, A498, VMRC, and TUHR10." (PMID 32259478, 2020). "Nevertheless, we would argue that RCC cell killing in our PDX model experiment was antigen specific, since the growth of the WT1-negative tumor was not suppressed, whereas that of the WT1-positive tumor in the same mouse was suppressed." (PMID 32259478, 2020). "Of 289 historically diagnosed EnOC cases identified with available tumour material, 112 WT1 negative cases were characterised by WES following rigorous pathology review." (PMID 33020491, 2020). "The tumor cells were robustly and diffusely positive for Trk, S100-protein, CD34, and nestin, but negative for CD56, SMA, desmin, myogenin, STAT6, EMA, CK, CD1a, CD21, CD35, CD43, WT-1(c-terminal), MelanA, HMB45, BRAF, and ALK." (PMID 32957984, 2020). "The Wilms tumor 1 (WT1) gene acts both as an oncogene and as a tumor suppressor." (PMID 31590362, 2019). "Notably, post-PDS patients had fewer WT1+ cells (mean 1718) than the NACT group (mean 4761; p = 0.08), possibly reflecting the substantial reduction in tumour mass at surgery." (PMID 31319587, 2019). "Herein, we described two sortase A-generated TCRm-ADCs (ESK-MMAE and Q2L-MMAE), against WT1 RMF/HLA-A*02:01 complex, which could specifically kill WT1 RMF/HLA-A*02:01 positive tumor cells in vitro and effectively inhibit tumor growth in the xenograft model." (PMID 31408937, 2019). "The 9-mer WT1-derived peptide 126–134, RMFPNAPYL (RMF), has been shown to be presented by HLA-A*02:01 molecules, which induces cytotoxic CD8+ T cells to kill WT1+ and HLA-A*02:01+ tumor cells." (PMID 31408937, 2019). "Immunohistochemical staining revealed that the tumor cells were positive for CK-7 and WT-1 and negative for CK-20 and ER." (PMID 31222668, 2019).
tumor (continued). "For example, the HGSC type HOV28T was WT1 negative unlike typical HGSC, but the original tumor tissue itself was WT1 negative, indicating the xenograft tissue well mirrored the original tissue." (PMID 31248002, 2019). "The WT1 gene acts as an oncogenic factor rather than as a tumor suppressor, and is involved in blocking the further differentiation of hematopoietic progenitor cells." (PMID 30678050, 2019). "WT1 has emerged as one of the most promising targets for AML immunotherapy, because of its oncogenic role in leukaemogenesis, its high expression in the majority of AML cells, and its ability to function as a tumour rejection antigen." (PMID 30678059, 2019). "The result clearly showed that 5′-regional expression of the WT1 gene was lacking in the tumor, being consistent with absence of immunoreactivity with the N-WT1 antibody at the protein level revealed by immunohistochemistry." (PMID 31103034, 2019). "The wild-type WT1 gene functions as an oncogene, which suggests that tumor escape via downregulation of WT1 is unlikely to occur." (PMID 30430205, 2019). "Irrespective of the type of tumor cell injected, the layer of PMCs in the xenografts remained intact, as demonstrated using Wt1 staining and was still present above the cancer cells that reached the stroma." (PMID 31086083, 2019). "IHC analysis showed that these areas were positive for CD209, CD14, and the tumour marker WT1, whereas they were negative for the lineage-specific marker CD45 (data not shown)." (PMID 30510965, 2018). "On the contrary, CD8+ T cells among the tumor infiltrating CD45.1+ immune cells did not significantly increase in mice treated with the WT1 combination vaccine compared to those treated with the WT1 CTL vaccine alone." (PMID 30542516, 2018). "WT1 expression was higher in tumours than in controls, but this was not due to increased endothelial WT1." (PMID 30374123, 2018). "It is notable, for example, that the NPI scores of ER-positive tumours (which have relatively high expression of WT1 compared to controls) showed no significant different to those that were ER-negative (which had similar WT1 expression to control tissues)." (PMID 30374123, 2018). "The expression of WT1 and p16 was significantly lower in DIPG tumor samples than NBS-HGG samples." (PMID 29932419, 2018). "WT1 is highly expressed in the blood vessels of most human tumours but not in the blood vessels in normal tissues." (PMID 30266964, 2018). "Although the remaining eight WT1-mutant tumours lacked WT1 protein expression, MUC-1 was consistently positive in UB-like structures." (PMID 29040332, 2017). "Tumor cells also had heterogeneous cytoplasmic staining positive for WT1 and negative for vimentin and α-sma antibodies (data not shown)." (PMID 28845162, 2017). "Distribution ≥50% of MSLN-, CA125-, and WT1-positive tumor cells were observed in 25%, 6%, and 45% of non-epithelioid MPM cases, respectively." (PMID 29100432, 2017).